INS (insulin)
Diseases named in the same sentence as INS in open-access papers (continued):
Sharing a sentence is not in itself a finding about the gene and the disease.
metabolic syndrome (continued). "Based on these results, APβG intake with a meal might be effective in controlling postprandial blood glucose and insulin levels, thereby reducing the risk of metabolic syndromes." (PMID 33467004, 2021). "However, it is well known that nitric oxide (NO) plays a crucial role in the pathogeneses of metabolic syndrome and is closely linked with insulin signaling." (PMID 34335851, 2021). "Berberine decreased blood glucose and the risk of metabolic syndrome, improved insulin sensitivity, stimulated weight loss, improved lipid metabolism, reduced the levels of hemoglobin A1C and triglyceride, increased the mRNA expression of adiponectin, and reduced leptin and resistin secretion." (PMID 33920079, 2021). "The increase in resistin in horses with severe insulin dysregulation may be related to the inflammatory changes associated with metabolic syndrome." (PMID 35011183, 2021). "The metabolic syndrome (MetS) is a constellation of metabolic abnormalities including abdominal obesity, dyslipidemia, hypertension, and disturbed glucose and insulin metabolism, all of which were well documented high-risk factors for both cardiovascular diseases (CVD) and type 2 diabetes mellitus." (PMID 34960095, 2021). "It has been proven by other researchers that there was a significant association between insulin level and Hcy concentration, which could link metabolic syndrome with Hcy." (PMID 34684648, 2021). "Adiponectin is a potent anti-inflammatory adipokine which also regulates insulin homeostasis, reducing the risk of many chronic diseases, including atherosclerosis, hypertension, nonalcoholic fatty liver, metabolic syndrome, cardiovascular disease, thrombosis, and asthma." (PMID 34746212, 2021). "IGFBP2, as a potential risk factor of insulin sensitivity, is related with metabolic syndrome." (PMID 33498859, 2021). "The present study was conducted to compare the effects of MH-76 and prazosin on some of the critical points associated with pro-inflammatory state and insulin signaling and their ability to affect adipocytokines in adipose tissue of fructose-fed rats, a well validated model of metabolic syndrome." (PMID 34069933, 2021). "In people with metabolic syndrome, episodic exposure of pancreatic beta cells to elevated levels of both glucose and free fatty acids (FFAs)—or glucolipotoxicity—can induce a loss of glucose-stimulated insulin secretion (GSIS)." (PMID 35052168, 2021). "In addition, dysbiosis is associated with metabolic syndrome, which has been proved to decrease insulin signaling and increase microglial proliferation, leading to progressive neurodegeneration in AD." (PMID 34366841, 2021). "Moreover, in the same study, it was demonstrated that this intervention caused modest, but potentially important, improvements in glycemic control, insulin sensitivity and dyslipidemia in participants with or at risk for T2DM." (PMID 33525638, 2021). "Importantly, hyperuricemia has a major causal role in fructose induced metabolic syndrome, likely due to inhibition of insulin-mediated endothelial nitric oxide synthesis." (PMID 34199607, 2021). "According to previous findings, greater energy intake later in the day is significantly associated with lower insulin sensitivity and night-time eating (25% or more of total energy consumed after 9 p.m.)is significantly associated with increased prevalence of metabolic syndrome." (PMID 34202475, 2021). "A lack of sex steroid may lead to delay of puberty, reduced bone density and size, obesity, impaired insulin sensitivity, and increased risk of dyslipidemia, hypertension, metabolic syndrome and cardiovascular diseases." (PMID 34413832, 2021). "Although the link between EC and metabolic syndrome is proven, the mechanisms by which metabolic syndrome causes EC are undetermined; this may be due to elevated serum values of metabolites (glucose, insulin, insulin-like growth factor, and triglycerides)." (PMID 34577868, 2021).
metabolic syndrome (continued). "Finally, treatment of diabetic rats with insulin also prevented body weight loss and proteinuria, decreased polyphagia, avoided dyslipidemia, and significantly decreased hepatic damage biomarkers." (PMID 32566072, 2020). "In analyses examining the individual components of the metabolic syndrome score, we found that maternal fish intake was most strongly inversely associated with the waist circumference and insulin level of children and was positively associated with the HDL cholesterol level of children." (PMID 32176304, 2020). "Leptin can improve dyslipidemia in insulin-deficient rodents." (PMID 33071988, 2020). "This agrees previous reports demonstrating that supplementation with high sucrose concentrations is effective for induction of metabolic syndrome in laboratory rats, causing increased body weight, insulin, triacylglycerol, TC, LDL-C, and free fatty acids, among other anomalies." (PMID 32492837, 2020). "Similarly, normoandrogenic PCOS was associated with relatively lower risks of metabolic syndrome, cardiovascular risk factors, and insulin sensitivity when compared with hyperandrogenic PCOS." (PMID 32309767, 2020). "This condition increases the risk of metabolic syndrome along with blood glucose and insulin." (PMID 32357485, 2020). "Short-term physical inactivity and a positive energy balance can have several consequences for health related to reduced insulin sensitivity, higher total body and central fat, and a proinflammatory state, which are all central risk factors for metabolic syndrome." (PMID 32466598, 2020). "These metabolic modifications observed in this study substantiated the claim in experimental models that high calorie-containing foods cause glucose levels to rise in the blood, insulin insensitivity and dyslipidemia all of which increases the development of cardiovascular related disorders." (PMID 33163962, 2020). "In addition, replacement of SFA with MUFA improves body composition and insulin sensitivity while reducing hyperglycemia and hypertension in individuals predisposed to metabolic syndrome." (PMID 32676029, 2020). "However, correlation analyses with clinical parameters revealed a positive correlation between plasma ADCY1 levels, TGL and insulin, suggesting a potential association with dyslipidemia and a prediabetic state, respectively." (PMID 32847122, 2020). "Gestational hypoxia also causes hypermethylation of the adiponectin gene promoter with concomitant decrease in adiponectin levels in male offspring, who are more susceptible to metabolic syndrome in adulthood, as indicated by hyperleptinaemia and decreased insulin sensitivity." (PMID 32494846, 2020). "The authors concluded that use of injected insulin predisposes to inflammation, atherosclerosis, hypertension, dyslipidemia, heart failure, and arrhythmias, showing that insulin therapy has an overall poorer safety profile than that found with several other therapies used to treat T2D." (PMID 33167495, 2020). "However, reduced insulin sensitivity and the associated compensatory hyperinsulinism are early findings in patients developing the metabolic syndrome, and are fundamental to the pathogenesis of these conditions." (PMID 33013688, 2020). "In a study investigating the gene–diet interactions of the CLOCK variants in metabolic syndrome patients, it was found that TT carriers of rs1801260 variant had higher insulin sensitivity, lower plasma insulin concentration and lower HOMA-IR after one year of low fat consumption." (PMID 31581435, 2019). "Indeed, therapies for fatty liver disease are aimed at reducing body weight and improving insulin sensitivity to alleviate the associated metabolic syndrome." (PMID 31836013, 2019). "The amelioration of glucose homeostasis abnormalities and metabolic syndrome could be even more relevant in women in the postmenopausal period, when weight loss and improved insulin sensitivity might contribute to reduce cardiovascular risk." (PMID 31191454, 2019).
metabolic syndrome (continued). "Interestingly, although IR has been considered the central driver of type 2 diabetes and metabolic syndrome, an alternative argument places IR as an adaptive biomarker of poor metabolic health and insulin hyperesponsivness as the root cause." (PMID 31331009, 2019). "In our study, compared with non-IR groups, the IR group had a higher prevalence of hypertension, higher levels of total cholesterol, fasting glucose and fasting insulin, and more advanced age, which all further confirmed that IR is closely associated with metabolic syndrome." (PMID 31249520, 2019). "A meta-analysis suggests that individuals living a sedentary lifestyle have a significantly higher T2D and metabolic syndrome risk, while physical activity contributes positively to preventing or delaying T2D progression either by affecting BMI or improving insulin sensitivity." (PMID 31685799, 2019). "Further, PCOS women showing biochemical androgen excess are more prone to reduced insulin sensitivity and dysglycemia, number of menstrual cycles in a year, elevated cardiovascular disease markers, dyslipidemia, and heightened predisposition to metabolic syndrome." (PMID 29670770, 2018). "Indeed, in a study from our group in subjects with the metabolic syndrome, higher plasma propionate levels were associated with a better insulin sensitivity after a 12-week of a wholegrain-based dietary intervention." (PMID 30213062, 2018). "Our present systematic review shows that objectively measured LPA was inversely associated with all-cause mortality risk and was favorably associated with some cardiometabolic risk factors, including WC, triglyceride levels, insulin, and the presence of metabolic syndrome." (PMID 29986718, 2018). "Recently, ectopic fat, such as hepatic and pancreatic fat, was more fully investigated in pediatric populations, and some authors proposed that its accumulation could contribute to the risk of metabolic syndrome and impaired insulin response." (PMID 29298340, 2018). "Not only lipid loci but also insulin-associated loci associated with metabolic syndrome." (PMID 30382898, 2018). "As a result, it promoted high insulin and dyslipidemia indicating the risk of metabolic syndrome." (PMID 29607311, 2018). "Reduced insulin sensitivity has been linked to alterations in cardiac and peripheral cardiovascular function including altered endothelial function, hypertension and dyslipidemia, as well as an increased risk of cardiovascular pathology in later life." (PMID 30154437, 2018). "Several intronic single nucleotide polymorphisms (SNPs) at the ARL15 locus have been associated with components of the metabolic syndrome and its sequelae including plasma adiponectin, insulin, HDL cholesterol, and triglyceride concentrations, and coronary artery disease." (PMID 29242557, 2017). "Injections of BDNF in the paraventricular nucleus (PVN) of obese rats fed HFD normalize energy intake, body weight, hyperlipidemia, hyperinsulinemia, and hyperleptinemia indicating that hypothalamic BDNF improves metabolic syndrome symptoms associated with insulin and leptin resistance." (PMID 28706476, 2017). "It has reported that insulin sensitivity is strongly associated with metabolic syndrome." (PMID 28673352, 2017). "This suggested that CLZ has direct effects on deficiency of insulin release and dyslipidemia." (PMID 28584269, 2017). "Therefore, an early and “aggressive” intervention based on lifestyle changes and insulin sensitizer drugs in subjects with dyslipidemia seems to be recommended because of the high risk of developing T2DM." (PMID 28199386, 2017). "Insulin sensitizing effects of RAS blockade have also been reported in clinical studies in patients with risk factors suggesting additional benefits of these drugs in a complex condition like metabolic syndrome." (PMID 28972997, 2017).
metabolic syndrome (continued). "Accordingly, intervention studies in men with a risk of developing metabolic syndrome, with olive leaf polyphenolic compounds (i.e., oleuropein and hydroxytyrosol), have shown significant improvements in insulin sensitivity and pancreatic β-cells secretory capacity after an oral glucose challenge." (PMID 29048364, 2017). "Rather-improving insulin sensitivity, by means of weight loss, dietary modifications, exercise and/or by pharmacological means, will result in improvement of several factors associated with the Metabolic syndrome in parallel." (PMID 29280741, 2017). "Growth hormone therapy in these children can also induce higher insulin levels which led to speculation that these patients may be at increased risk for development of metabolic syndrome." (PMID 27803155, 2016). "Especially in patient with the metabolic syndrome, increasing insulin sensitivity by metformin might be associated with improvements of diastolic function." (PMID 27977774, 2016). "Thus, in metabolic syndrome patients, insulin secretion increases, causing hyperinsulinemia and the exhaustion of the β cells in pancreatic islets." (PMID 27733131, 2016). "According to studies in the early 1990s, when compared with the Nunavik Inuit surveyed in a similar time frame, Cree adults had much higher cardiometabolic risk factors (low HDL-c, high TG, high TC:HDL-c, high insulin and metabolic syndrome), and also had 1.7 times lower plasma n-3 LC-PUFA levels." (PMID 27427488, 2016). "In models of SB bouts adjusted for MVPA, breaking up sedentary time into more short sedentary bouts (1–15 min) was associated with lower levels of adiposity, fasting insulin and metabolic syndrome, although the effect size for MVPA was larger than for short bouts of SB." (PMID 26980183, 2016). "Because higher insulin levels are indicative of metabolic syndrome and both have previously been associated with increased risk of developing and dying from prostate cancer, we initially predicted that higher insulin levels would also correlate with shorter time to castration-resistant progression." (PMID 27599544, 2016). "We suggest that in subjects with metabolic syndrome, endothelial function is impaired by multiple cardiovascular risk factors exclusively when under the condition of insulin insensitivity and also that defining metabolic syndrome can effectively predict impairment of endothelial dysfunction." (PMID 27188597, 2016). "In order to provide better prenatal care and improved health outcomes, it is important that studies be carried out to evaluate the effects of TH-EDCs on lipid levels, insulin sensitivity, and glucose tolerance as they are significant underlying factors in the development of metabolic syndrome." (PMID 26989557, 2016). "This, combined with the differences in fasting glucose and in insulin sensitivity, suggests that catch-up growth in this model may be associated with increased risk of metabolic syndrome." (PMID 26040642, 2015). "Metabolic syndrome could influence breast cancer risk through effects on interrelated signalling pathways involving insulin, estrogens, growth factors, and cytokines." (PMID 26030767, 2015). "In summary, HbA1c and insulin measurements were highly associated with metabolic syndrome traits." (PMID 26241903, 2015). "Treatment with L-arabinose has proven to cause a reduction of insulin concentrations and elevated insulin sensitivity in metabolic syndrome rats; thus, these changes could be partially responsible for the lowering effect on blood pressure." (PMID 26652604, 2015). "Among non-metabolic syndrome patients, a small insulin elevation identified risk factor clustering." (PMID 26241903, 2015).
metabolic syndrome (continued). "With a similar cost, however, fasting insulin provides a measurement that may be more closely linked to the pathways conducing to the metabolic syndrome." (PMID 26241903, 2015). "The insulin pathway is involved in the pathogenesis of the metabolic syndrome and an increased body mass index increases the risk of PsA development in patients with cutaneous psoriasis, supporting a link between fat-mediated inflammation and joint involvement." (PMID 26086874, 2015). "A reduced glucose uptake causes an attenuated insulin response that may prevent the development of diseases related to the metabolic syndrome." (PMID 26101587, 2014). "For example, hypertension is frequently associated with metabolic syndrome, and insulin-mediated stimulation of PT transport may play a role in this association." (PMID 24982885, 2014). "In particular, the stimulatory effect of insulin on PT transport may be involved in the pathogenesis of hypertension associated with metabolic syndrome." (PMID 24982885, 2014). "Since decreased insulin sensitivity is linked to metabolic syndrome (MS), decreased adiponectin levels may be related to its development." (PMID 24568287, 2014). "The aim of this study was to assess the potential impact of a family history of metabolic syndrome (fhMetS) on the risk of metabolic disorders (abnormal body mass, lipid profile, glucose metabolism, insulin resistance, and blood pressure) in healthy young individuals." (PMID 25024747, 2014). "While the molecular mechanisms remain unclear, increased ROS is associated with multiple aspects of the metabolic syndrome including obesity, fatty liver disease, and diabetes, and is thus an attractive therapeutic target to improve insulin sensitivity." (PMID 24672550, 2014). "In addition, serum ferritin has been correlated with dyslipidemia biomarkers, hepatic enzymes, and negatively associated with adiponectin, an insulin sensitizing adipokine that is decreased in diabetic patients." (PMID 24904420, 2014). "Persistently high blood glucose and insulin as a result of a diet high in high GI carbohydrate may cause metabolic abnormalities giving rise to dyslipidemia that in turn increase the risk of stroke risk." (PMID 23717392, 2013). "LPIN1 SNPs and haplotypes that may confer variability in the protein activity have been associated with several components of the metabolic syndrome, including body mass, insulin levels, resting metabolic rate and to responsiveness to insulin sensitizers." (PMID 23394097, 2013). "However, in a recent meta-analysis conducted in 8504 subjects the LPIN1 rs13412852 T allele was associated with lower BMI and insulin levels, confirming that it possibly represents a protective factor towards metabolic syndrome alterations." (PMID 23394097, 2013). "Finally, we did not measure hormones, which are involved in the association between sleep quality and metabolic syndrome, such as insulin resistance, sympathoadrenal activity, ghrelin and leptin." (PMID 23342127, 2013). "Although adults with hypertension are more likely to be insulin resistant and hypertension tends to cluster with other metabolic risk factors, there are currently no guidelines for treating hypertension specifically in individuals with metabolic syndrome." (PMID 23586038, 2013). "Some authors have suggested components of the metabolic syndrome, in particular insulin-resistance and subsequent hyperinsulinemia, to be the underlying link, which may reflect the growth-promoting effects of insulin." (PMID 23072404, 2012). "Polymorphisms of three regions seem to have co-evolved to establish a haplotype that may serve to coordinate metabolic phenotypes of fasting glucose, insulin, body mass index (BMI) and predisposition to metabolic syndrome." (PMID 22680924, 2012). "In addition, studies have shown that obese girls with vitamin D deficiency presented lower insulin sensitivity, and adolescents with reduced levels of vitamin D had increased risk of metabolic syndrome." (PMID 22681928, 2012).